REEP1 (receptor accessory protein 1)
Description:
Required for endoplasmic reticulum (ER) network formation, shaping and remodeling; it links ER tubules to the cytoskeleton. May also enhance the cell surface expression of odorant receptors. May play a role in long-term axonal maintenance.
Synonyms: C2orf23; SPG31; FLJ13110; Yip2a; DSMA6; HMN5B; HMND12; HMNR6
Tractability: Antibody: UniProt predicts a signal peptide or a membrane-spanning region. PROTAC: ubiquitination databases record sites on it; its protein half-life has been measured.
Gene: Protein-coding gene on chromosome 2 (86,213,993 to 86,338,083, reverse strand). Ensembl gene ENSG00000068615.
Subcellular location: Membrane; Mitochondrion membrane; Endoplasmic reticulum
Pathways (Reactome):
Sensory Perception: Expression and translocation of olfactory receptors
Gene Ontology:
Molecular function: microtubule binding; olfactory receptor binding; protein binding
Biological process: endoplasmic reticulum tubular network organization; protein insertion into membrane
Cellular component: cytoplasm; endoplasmic reticulum; membrane; mitochondrial membrane; cytoplasmic microtubule; endoplasmic reticulum membrane; endoplasmic reticulum tubular network
Genetic constraint (gnomAD): Loss-of-function variants: 21 observed, 33.06 expected, observed/expected ratio (o/e) 0.64, 90% interval 0.45 to 0.92. The upper end of that interval is the gene's LOEUF score, 0.92, which puts it in group 3 of 6, group 1 being the genes least tolerant of losing a copy. Missense variants: 278 observed, 352.07 expected, observed/expected ratio (o/e) 0.79, 90% interval 0.71 to 0.87. Synonymous variants: 113 observed, 135.2 expected, observed/expected ratio (o/e) 0.84, 90% interval 0.72 to 0.98.
Homologues: Orthologues: chimpanzee REEP1 (99% identical), dog REEP1 (96% identical), mouse Reep1 (96% identical), rat Reep1 (96% identical), pig REEP1 (94% identical), guinea pig REEP1 (93% identical), macaque REEP1 (92% identical), rabbit REEP1 (90% identical), tropical clawed frog reep1 (69% identical), zebrafish reep1 (58% identical), Caenorhabditis elegans T19C3.4 (34% identical), Drosophila melanogaster CG5539 (21% identical), and 5 more. Paralogues in human: REEP2 (52% identical), REEP4 (48% identical), REEP3 (46% identical), REEP5 (17% identical), REEP6 (16% identical).
Diseases named in the same sentence as REEP1 in open-access papers:
REEP1 is named in the same sentence as 45 diseases in open-access papers, as found by Europe PMC text mining. Sharing a sentence is not in itself a finding about the gene and the disease. The quoted sentences say what the papers report.
hereditary spastic paraplegia (30 papers, 2013 to 2026). Hereditary spastic paraplegias (HSP) comprise a genetically and clinically heterogeneous group of neurodegenerative disorders characterized by progressive spasticity and hyperreflexia of the lower limbs. "REEP1 loss‐of‐function causes hereditary spastic paraplegia due to degeneration of cortical motoneuron axons." (PMID 41268727, 2026). "In cultured cells harboring hereditary spastic paraplegias-associated REEP1 mutations, fewer MERCs were observed compared with wild-type cells, leading to the notion that ER-localized REEP1 shapes mitochondria." (PMID 39133213, 2024). "Several hereditary spastic paraplegia-causing mutations in REEP1 appear at the oligomeric interfaces identified here, suggesting compromised self-association of REEP as a pathogenic mechanism." (PMID 37147312, 2023). "Mutations in ER-shaping proteins such as Spastin, ATL1, RTN2 or REEP1 that couple the tubular ER network with microtubule dynamics cause hereditary spastic paraplegia." (PMID 35650592, 2022). "Mutations in a genomic region coding an ER-resident protein Reep1 is associated with hereditary spastic paraplegias (HSPs) and distal hereditary motor neuropathy." (PMID 34095118, 2021). "Some human hereditary spastic paraplegias result from mutations in REEP1 which is required for ER network formation." (PMID 30791866, 2019). "Most recently, receptor expression enhancing protein 1 (REEP1), which is linked to hereditary spastic paraplegia (HSP) and some hereditary motor neuron disorders, has been shown to influence ER–mitochondria associations." (PMID 26899735, 2016). "A previous study showed that REEP1 variants were related to hereditary spastic paraplegia (HSP)." (PMID 37761904, 2023). "Finally, it is worth mentioning that mutations inthe spastin, strumpellin, or REEP1 genes cause hereditary spastic paraplegia (HSP)." (PMID 37366507, 2022). "Additionally, REEP1 and atlastin-1 were identified separately as genes implicated in the development of the neurodegenerative disorder hereditary spastic paraplegia (HSP)." (PMID 36060263, 2022). "Mutations in the REEP1 proteins are associated with hereditary spastic paraplegias (HSP), a family of inherited neurological disorders characterized by spastic weakness in the extremities, which is partly reminiscent of symptoms induced by neurotropic flaviviruses." (PMID 32298390, 2020). "ATL1, RTN2, SPAST and REEP1 are the causative genes of hereditary spastic paraplegia (HSP)." (PMID 29310658, 2018). "Mutations in spastin, strumpellin, or REEP1 cause hereditary spastic paraplegia (HSP), a disease characterized by axonal degeneration." (PMID 28389476, 2017). "Hereditary spastic paraplegia (HSP) is a genetically heterogeneous disease caused by mutations in many genes, including those encoding spastin, strumpellin, or REEP1." (PMID 28389476, 2017). "Mutations in REEP1 and REEP2 cause Hereditary Spastic Paraplegia, but the function of these four REEP proteins remains enigmatic." (PMID 39368994, 2024). "REEP1 and REEP2 are enriched in neurons, and mutations in these proteins are linked to hereditary spastic paraplegia (HSP) and distal hereditary motor neuropathy type Vb (HMN5B), two related, inherited neuropathies caused by axonal shortening of motor neurons." (PMID 39368994, 2024). "Receptor expression-enhancing protein 1 (REEP1) is an endoplasmic reticulum (ER) resident protein involved in the SPG31 form of Hereditary Spastic Paraplegia (HSP), a neurodegenerative disorder affecting motoneurons." (PMID 31803000, 2019). "In addition, REEP1 mutations were found to be a genetic cause for the neurodegenerative disorder hereditary spastic paraplegia (HSP)." (PMID 24098485, 2013). "Furthermore, transcripts of disease-associated genes, such as BSCL2-206, REEP1-201, UCHL1-207/209 and KIF5A-202, all associated with hereditary spastic paraplegia (HSP), were significantly differentially expressed." (PMID 40735840, 2025).
hereditary spastic paraplegia (continued). "Hyper-phosphorylation of Drp1 at Ser-637 induced abnormal mitochondrial dynamics in somatic cells isolated from hereditary spastic paraplegia patients; this disturbance is mediated by impaired interactions between receptor expression enhancing protein 1(REEP1) and PGAM5." (PMID 28098754, 2017). "REEP1 mutations are associated with hereditary spastic paraplegias (HSP) due to its lack of cytoplasmic region interaction with microtubules for the ER network, for which the HSP was found in the Chinese population." (PMID 37238941, 2023). "Receptor expression-enhancing protein 1 (REEP1) knockout mice; Model for hereditary spastic paraplegias that are genetic neurodegenerative disease." (PMID 35615361, 2022).
Spastic paraplegia (10 papers, 2015 to 2024). Complete loss of the ability to move the lower limbs accompanied by spasticity of the lower limbs. "Spastic paraplegia (SPG) has been linked to mutations in other family members (REEP1/SPG31 and REEP2/SPG72)." (PMID 39262575, 2024). "Mutations in REEP1 (OMIM 609139) and REEP2 (OMIM 609347) are associated with spastic paraplegia (SPG) types 31 (SPG31), and 72 (SPG72)." (PMID 29770609, 2018). "The REEP4 paralogs, REEP1 and REEP2, are associated with spastic paraplegia." (PMID 39262575, 2024). "A small number of mutations in REEP1 (MIM 609139) have been reported to cause several neuromuscular disorders, such as the dominant dHMN5B (MIM 614751), also known as distal spinal muscular atrophy type 5B (dSMA5B), and dominant spastic paraplegia-31 (SPG31, MIM 610250)." (PMID 34193129, 2021). "Genetic tests performed before WES excluded Huntington’s disease (IT15), spinal muscular atrophy (SMN1), spinal bulbar muscular atrophy (AR), primary torsion dystonia (DYT1), and the common forms of spastic paraplegias (SPG4, REEP1, ATL1, SPG7)." (PMID 25957632, 2015).
distal hereditary motor neuropathy (3 papers, 2016 to 2026). "Mutations in the human DP1 gene REEP1 are associated with Hereditary Spastic Paraplegia type 31 and distal hereditary motor neuropathy." (PMID 39312180, 2024).
Hereditary Spastic Paraplegia type 31 (3 papers, 2012 to 2024). "The six REEP proteins include REEP1, which is mutated in hereditary spastic paraplegia 31 (one of a group of disorders characterized by progressive weakness and stiffness of the legs), and REEP4, loss of which causes paralysis in Xenopus." (PMID 22870394, 2012). "Mutation of REEP1 causes hereditary spastic paraplegia 31 in humans, which is characterized by progressive weakness and stiffness of the legs, and mutation of REEP4 causes lower body paralysis in an animal model." (PMID 22870394, 2012). "Genetic mutations in the human DP1 protein REEP1 that are associated with autosomal dominant hereditary spastic paraplegia type 31 (SPG31) and distal hereditary motor neuropathy type V (dHMN5) are found at this dimer interface." (PMID 39312180, 2024).
breast carcinoma (2 papers, 2010 to 2019). "In summary, we retrospectively identified five bone metastases‐related genes (KRT23, REEP1, SPIB, ALDH3B2, and GLDC) and constructed a gene expression signature‐based nomogram (GESBN) model for breast cancer patients by bioinformatics analysis." (PMID 30575323, 2019). "NRIP3, TMC5, REEP1 and NKAIN1, whose expression had not previously been described in breast cancer, were also deregulated in the PIK3CA-mutated breast tumors." (PMID 21209903, 2010).
dementia (2 papers, 2011 to 2025). Loss of intellectual abilities interfering with an individual's social and occupational functions. "Indeed, ASTN1 is known to regulate neuronal migration in cortical regions of developing brain, SNCA is associated with neurodegeneration and dementias, including links to FTLD-TDP in PGRN+ patients and REEP1 has been implicated in corticospinal neurodegenerative disorders." (PMID 22032330, 2011).
carpal tunnel syndrome (1 paper, 2025). Entrapment of the median nerve in the wrist that is characterized by numbness, tingling and painful movement. "For instance, PN has been documented in SPG31 due to REEP1 mutations, with some cases presenting with carpal tunnel syndrome." (PMID 41164410, 2025).
colon cancer (1 paper, 2018). "Independent experiments confirmed several target genes, including PLOD2, HADH, LCOR and REEP1 as non-canonical target genes in various colon cancer cells." (PMID 29453334, 2018). "Silencing of ATF2 revealed downregulation of PLOD2, HADH, LCOR and REEP1 mRNA expression; thus suggesting ATF2 as the transcription factor in non-canonical Wnt signaling in colon cancer cells." (PMID 29453334, 2018).
distal hereditary motor neuropathy type V (1 paper, 2021). "Mutations in REEP1, the cause of SPG31, have been shown to cause distal hereditary motor neuropathy type V." (PMID 33646413, 2021).
ovarian carcinoma (1 paper, 2020). A malignant neoplasm originating from the surface ovarian epithelium. "However, only AOX1 of top five down-regulated genes was verified to be decreased in expression for expanding sample of ovarian cancers, with that of REEP1, BNC1, HAND2, and GSDME unchanged." (PMID 33135729, 2020).
primary progressive MS (1 paper, 2021). "For example, SPG2 has been shown to mimic MS, and rare variants in genes including KIF5A and REEP1 were identified in patients with primary progressive MS." (PMID 33646413, 2021).
neurological disorder (2 papers, 2018 to 2023). "Interestingly, mutations in genes involved in the regulation of ER biogenesis and maintenance, such as Valosin-containing protein (VCP), Atlastin-1 (ATL1), Spastin (SPAST), Reticulon 2 (RTN2), and Receptor expression enhancing protein 1 (REEP1) have been linked to neurological diseases." (PMID 29310658, 2018). "Mutations in the receptor expression-enhancing protein 1 gene (REEP1) are associated with hereditary spastic paraplegia type 31 (SPG31), a neurological disorder characterized by length-dependent degeneration of upper motor neuron axons." (PMID 36834939, 2023).
tumor (1 paper, 2010). "NRIP3, TMC5 and REEP1 are differentially expressed in various other tumor types." (PMID 21209903, 2010).
REEP1 also shares sentences with these, for which no sentence is quoted: cerebellar ataxia (4 papers); amyotrophic lateral sclerosis (2); autosomal dominant spastic paraplegia 31 (2); cancer (2); neurodegenerative disease (2); neuropathies (2); ataxia and (1); autosomal dominant spastic paraplegia (1); autosomal dominant spastic paraplegia 3A (1); autosomal dominant spastic paraplegia 4 (1); Brain atrophy (1); breast tumors (1); Cerebellar atrophy (1); distal hereditary motor neuronopathy type VB (1); Dystonia (1); epilepsy (1); Genetic neurodegenerative disease (1); Huntington disease (1); lipodystrophy (1); metabolic disorders (1); movement disorder (1); muscular atrophy (1); myelodysplastic syndrome (1); optic atrophy (1); peripheral neuropathy (1); primary torsion dystonia (1); retinitis pigmentosa (1); Spastic paraparesis (1); Spasticity (1); spinal muscular atrophy (1).
A further 2 diseases each share a sentence with REEP1 in 1 paper.